RUNX1 (RUNX family transcription factor 1)
Diseases named in the same sentence as RUNX1 in open-access papers (continued):
Sharing a sentence is not in itself a finding about the gene and the disease.
infection (41 papers, 2009 to 2025). The state of being infected such as from the introduction of a foreign agent such as serum, vaccine, antigenic substance or organism. "Analysis of CD4+ T-cell populations shows that upon activation of naïve CD4+ T-cells (a population relatively refractory to infection) the expression levels of RUNX1, RUNX3 and CBF-β drop (correlating with greater susceptibility to infection)." (PMID 24651404, 2014). "Notably, the role of each of the five genes (ITGAM, IRF-9, LY6E, PSTPIP2, and RUNX1) has been linked to response to infection in the literature." (PMID 36900096, 2023). "In addition, because Gcsfr-depleted larvae were more susceptible to infection than Runx1-depleted larvae (in which both neutrophil and macrophage numbers were reduced), it is possible that Gcsfr regulates other aspects of neutrophil biology, not only neutrophil number." (PMID 28954734, 2017). "Our results show for the first time that both viral gene expression and the viral genome are lost during a persistent infection of B cells expressing RUNX1 leukemic fusion genes." (PMID 41497616, 2025). "Because RUNX1 translocations enhanced viral levels during the acute phase of infection it is possible that other activities of the virus are also enhanced." (PMID 41497616, 2025). "While the length of time required for loss of hexon mRNA varies between three replicate infections, expression was robustly reduced in RUNX1/MTG8 or ETV6/RUNX1-expressing B cells between 7 to 10 weeks post infection." (PMID 41497616, 2025). "IRF-9 (OR = 1.750, 95% CI = 1.16 to 2.638), ITGAM (OR = 1.533, 95% CI = 1.047 to 2.244), PSTPIP2 (OR = 2.191, 95% CI = 1.293 to 3.711), and RUNX1 (OR = 1.974, 95% CI = 1.069 to 3.646) had a significant expression with positive infection status." (PMID 36900096, 2023). "A549 cells were infected with PR8 at MOI of 0.1, 1, and 5, and the expression of RUNX1 was detected by Western blot and qRT-PCR at 12 h post-infection (h.p.i.)." (PMID 35248104, 2022). "On contrary, levels of interferon-gamma (IFN-γ) and Runt-related transcription factor 1 (RUNX1) were found increased during early infection (UC1)." (PMID 31614626, 2019). "Infection of EBV negative BL31 cells with wild-type EBV or revertant viruses reduced RUNX1 protein expression as expected, but infection with EBNA3B knockout viruses resulted in 6.7-fold higher protein levels than wild-type EBV infected cells." (PMID 26883634, 2016). "Our finding reveal that the RUNX1 leukemic fusion products may expel adenovirus from persistently infected B cells while an epigenetic echo of the infection remains in the cells." (PMID 41497616, 2025). "Cells expressing the RUNX1 fusion gene, or cells stably transfected with the empty vector, were infected with adenovirus and evaluated for repression of cellular genes at late times post-infection when most of the virus was lost from the population." (PMID 41497616, 2025). "Furthermore, like EG neutrophils, those within Tg(Runx1:cebpb-CG2;lyz:DsRed2) larvae enhance expression of genes associated with mitochondrial biogenesis following infection and have greater mitochondrial mass." (PMID 37672586, 2023). "Then, we found that CGN, MAP3K5, GATA4 and RUNX1 related to tight junction were upregulated during DTMUV infection, indicating that these genes may play an important role in DTMUV entry." (PMID 35585616, 2022). "We also examined RUNX1 expression in A549 cells at different time points after PR8 infection." (PMID 35248104, 2022). "Notably, the intracellular expression of Runx1 and Runx3 remained unchanged despite SbRLD or SbSLD infection or SAG treatment (right two panels)." (PMID 33370418, 2020). "Treatment with SIRT1 agonist suppressed the FAK phosphorylation, and FAK-dependent increase in Pu.1 and Runx1 involved in Mφ proliferation and polarization, and also suppressed the NFκB activity required for proinflammatory activation of Mφ in response to Tc infection." (PMID 31905606, 2019).
infection (continued). "It is hypothesized that during infection of bovine mammary epithelial cells by S. agalactiae, genes such as tsf, prfB, and infC, which are involved in RNA binding, infiltration of host cells, and disruption of lncRNA targeting of RUNX1 and BCL2L11." (PMID 39272372, 2024). "Similar to EG neutrophils, those within Tg(Runx1:cebpb-CG2;lyz:DsRed2) larvae enhance expression of mitochondrial respiratory complex subunits and assembly factors associated with mtROS production following infection and have enhanced bactericidal activity through an mtROS-dependent mechanism." (PMID 37672586, 2023). "There were statistically significant associations between positive infection status and four of the five genes: IRF-9 (OR = 1.750, 95% CI = 1.16–2.638), ITGAM (OR = 1.533, 95% CI = 1.047–2.244), PSTPIP2 (OR = 2.191, 95% CI = 1.293–3.711), and RUNX1 (OR = 1.974, 95% CI = 1.069–3.646)." (PMID 36900096, 2023). "The infection of primary blasts isolated from the bone marrow of pre-B ALL patients with a lentiviral vector expressing miR-181a increased the level of miR-181a by an average of 2.5-fold (range from 1.5- to 3-fold) in three ETV6/RUNX1-positive samples compared with the controls." (PMID 26580398, 2015). "The transcript levels of the myeloid lineage-related genes RUNX1, vWF, ITGB3, PU.1 and GM-CSF were significantly increased by 7 days of Omicron PsV infection." (PMID 40025168, 2025). "Runx1 overexpressing SMARTA cells (OE) produced fewer Tcf1+ CXCR5+ and Bcl6+ Tfh cells by percent at 3.5 days post infection." (PMID 39677644, 2025). "Twenty-eight days into the infection, hexon, E2A and E3-gp19K mRNA levels were significantly reduced in cells expressing either ETV6/RUNX1 or RUNX1/MTG8RUNX1 compared to expression levels in empty vector containing cell." (PMID 41497616, 2025). "Again, there was a considerable amount of heterogeneity in the copy number present during each infection but the fold change significantly increased 6-fold in ETV6/RUNX1-positive cells and 5-fold in RUNX1/MTG8-positive cells on average in each infection." (PMID 41497616, 2025). "Phosphorylation of IRF3 and STAT1 was enhanced when RUNX1 was knocked down, while phosphorylation of IRF3 and STAT1 were markedly decreased in the cells with RUNX1 overexpression compared with the control cells at 3, 6, and 9 h post PR8 infection." (PMID 35248104, 2022). "It indicated RUNX1 would facilitate H1N1 CA04, H3N2 ZJ163 and H9N2 JSC1 infection as well, because IFN-β and ISGs are crucial in the antiviral response." (PMID 35248104, 2022). "We performed qRT-PCR to compare the mRNA levels of IFNB1 between RUNX1-knockdown and control cells after PR8 infection." (PMID 35248104, 2022). "During the early infection (UC1), expression of RUNX1 was found elevated by the fold change value of 1.15 compared to endemic control." (PMID 31614626, 2019). "Our results partly correlate with those of a previous study showing that RUNX1 binds to CD82 in macrophages and suppresses MTB-induced infection and inflammation." (PMID 29760437, 2018). "We found a strong interaction between RUNX1 and CD82 promoter regions in BMDMs after MTB Rv infection." (PMID 29760437, 2018). "The ability of Vif to counteract repression mediated by RUNX1 and CBF-β in a spreading infection was monitored using a ΔVif virus." (PMID 24651404, 2014). "Viral stocks were harvested for three days and used for the infection/transduction of the transgenic model cell lines expressing the activated oncogenes AML1-ETO and RUNX1(K83N)." (PMID 22649608, 2009). "Furthermore, genes associated with inflammaging (IFNα, IL1β, NLRP3, IL6, IL1R and p16) and myeloid lineage (RUNX1, Fil1, CD150, PU.1 and GM-CSF) genes that were upregulated by Omicron PsV infection were downregulated by NGO treatment." (PMID 40025168, 2025).
infection (continued). "As the infection progressed, only a small fraction of the amount of viral DNA was retained in RUNX1 fusion containing cells as compared to translocation negative samples at the same time post infection." (PMID 41497616, 2025). "Both RUNX1 and BCL2L11 undergo abnormal alternative splicing during infection." (PMID 39272372, 2024). "The induction of Lgr5 was fairly specific, as other gastric stem cell markers, such as Sox2, Troy, Runx1, Lrig1, and others were not induced as a consequence of infection; an exception was Ascl2, the expression of which mirrored that of Lgr5." (PMID 39191487, 2024). "Additionally, RUNX1 knockdown increased IFN-β and ISGs production while RUNX1 overexpression compromised IFN-β and ISGs production upon PR8 infection in A549 cells." (PMID 35248104, 2022). "As observed before, MPCi treatment did not affect the kinetics of the primary CD8+ T cell response when transferred into naive hosts followed by Listeria-SIINFEKL infection and neither did RUNX1 deletion." (PMID 35452600, 2022). "Our current data reveals that the presence of ETV6/RUNX1 does not inhibit subsequent infections with adenovirus and, in fact, may enhance the level of virus present during acute infection." (PMID 41497616, 2025). "On the contrary, the loss of Pax5 is critical for ETV6/RUNX1+ B-ALL developed, as the onset of the disease in Sca1-ETV6-RUNX1 + Pax5-het mice (62.5%) is drastically increased even in the absence of exposure to infections, compared to Sca1-ETV6-RUNX1 mice (10.75%) and exposed to infections." (PMID 34336858, 2021). "However, neither SAG treatment nor LD infection had any effect on Runx1 and Runx3 expression in BMDCs (right two panels)." (PMID 33370418, 2020). "RUNX1, as a T-cell specific transcription factor capable of suppression or activation of target promoters, may alter the transcription of the viral LTR during cellular infection." (PMID 24651404, 2014). "Here we show that the common leukemic fusion proteins, ETV6/RUNX1 or RUNX1/MTG8, reduce adenovirus persistence in a B-lymphocyte line but do not dampen the initial acute infection phase." (PMID 41497616, 2025). "The common RUNX1 leukemic fusion genes ETV6/RUNX1 and RUNX1/MTG8 had no impact on viral gene expression during the acute phase but accelerated the decrease in viral gene expression and viral DNA replication during the persistent phase of infection." (PMID 41497616, 2025). "However, some genes, such as Jak2, Notch2, and Runx1, were up-regulated in KRAS+ mice regardless of infection status." (PMID 33310760, 2021).
blood cancers (13 papers, 2018 to 2025). "In FVPTC samples, LGALS3, an IA gene, is strongly associated with genes associated with blood cancers (RUNX1, BCL2L1, CBFB, and TNFRSF1A), suggesting a strong immune association in LGALS3 activity." (PMID 31443155, 2019). "Although the focus of Runx1 research has been predominately in the blood cancer field, recent evidence suggests that Runx1 has more widespread functions than previously considered." (PMID 37936072, 2023). "Transcription factor activity is usually regulated by multiple phosphorylation sites, for example, transcription factor RUNX1 is considered to be a major regulator of hemopoiesis and plays an important role in both hematopoietic system tumors and solid tumors." (PMID 35397606, 2022). "Notably, specific genes like RUNX Family Transcription Factor 1 (RUNX1) and RUNX Family Transcription Factor 2 (RUNX2), have been demonstrated to play significant roles in both normal hematopoiesis and the development of blood cancers." (PMID 40426895, 2025).
cardiovascular disease (10 papers, 2020 to 2025). "Higher expression of the hematopoietic transcription factor RUNX1 target F13A1 was associated with acute events in patients with cardiovascular disease receiving aspirin or ticagrelor." (PMID 41583468, 2025). "Since Runx1 has been identified as a new therapeutic target for developing drugs to treat cardiovascular diseases, it is important to get a better understanding of its expression patterns and regulatory mechanisms." (PMID 37936072, 2023). "Runx1 directly targets phosphatidylcholine transfer proteins in patients with cardiovascular diseases." (PMID 34725565, 2021). "Recently, several studies have reported that Runx1 may be a promising therapeutic target for cardiovascular diseases." (PMID 34725565, 2021). "An increasing number of studies are providing experimental support for this observation and as a result, the number of validated RUNX1 miRNA targets reported is continuously increasing, including the identification of RUNX1 miRNA targets which have known links to cardiovascular disease." (PMID 32154891, 2020). "Consequently, this research has the potential to usher in new therapeutic strategies in the realm of clinical investigations, thereby highlighting the crucial importance of the interaction between Brg1 and RUNX1 within the mechanisms of cardiovascular diseases." (PMID 39726787, 2024). "Runt-related transcription factor-1 (RUNX1), a key member of the core-binding factor family of transcription factors, has emerged as a novel therapeutic target for cardiovascular disease." (PMID 37936072, 2023).
hematological cancers (9 papers, 2008 to 2022). "Rearrangements or mutations of RUNX1 are associated with multiple hematopoietic neoplasms." (PMID 35241129, 2022). "Despite the importance of Aml1/Runx1 transcriptional factor in hematological cancers, the regulatory mechanisms involved in the controlling Aml1/Runx1 gene transcription during gliomagenesis remain poorly understood." (PMID 34440820, 2021). "The resulting chimeric protein termed AML-ETO retains the ability to bind RUNX1 target genes while exerting the transcription repression function of ETO, silencing RUNX1 genes contributing to the development of various hematopoietic cancers, most notably AML." (PMID 27150584, 2016). "Before our proteomic identification of SAIL in hematologic cancer samples, it had previously been described as a transcriptional target of RUNX1/AML1 expressed during the development of the mouse hematologic system." (PMID 26024286, 2015). "We do not believe that as a transcription factor and master regulator of hematological cancers, RUNX1 will alter the function of only one oncogenic molecule, but multiple molecules in the same pathways, and our analyses and functional assays are carefully designed to study these effects." (PMID 18671852, 2008).
cardiac disease (6 papers, 2018 to 2026). "Our results confirm the translational potential of RUNX1 as a novel therapeutic target in MI, with wider opportunities for use across a range of cardiac diseases where RUNX1 drives adverse cardiac remodelling." (PMID 37433039, 2023). "The key findings of our study will likely initiate further research into the beneficial effects of decreasing Runx1 expression in alternative animal models of cardiac disease." (PMID 29030345, 2018). "Increased Runx1 expression has been observed in a wide range of cardiac and non-cardiac diseases." (PMID 37433039, 2023). "Further investigation is now necessary to explore whether RUNX1 acts on similar targets in cardiac muscle and to understand the consequence of these RUNX1 interactions in the context of cardiac disease." (PMID 32154891, 2020). "The findings that RUNX1 can act as both a positive and negative regulator of NF-κB signalling is particularly intriguing, as NF-κB is a major orchestrator of the inflammatory actions of cytokines in heart disease." (PMID 32154891, 2020).
adenocarcinoma (4 papers, 2014 to 2020). A common cancer characterized by the presence of malignant glandular cells. "Our data also showed that reduced RUNX1 expression was associated with poor overall survival in adenocarcinomas." (PMID 32498288, 2020). "An early microarray profiling study comparing adenocarcinoma metastasis with primary adenocarcinoma tumors identified Runx1 as one of 17 genes signature that associate with metastasis." (PMID 28407681, 2017). "Adenocarcinoma patients with reduced RUNX1 expression showed 1.97-fold (95% confidence interval = 1.16–3.44, p = 0.01) higher hazard ratio for death than those without." (PMID 32498288, 2020). "Cox proportional hazards analysis also showed that overall survival of adenocarcinoma patients with reduced RUNX1 expression was approximately 1.97 (95% CI = 1.16–3.44; p = 0.01) times poorer than in those without, after controlling for age, recurrence, and pathologic stage." (PMID 32498288, 2020). "Here, we report for the first time in TRAMP mice, dynamic expression changes of the transcription factors, Runx1 and Runx2, and microRNAs that contribute to deregulated expression of Runx proteins, during the transition of normal prostate tissue to adenocarcinoma." (PMID 27634876, 2016). "The median survival of adenocarcinoma patients with and without reduced RUNX1 expression was 41 and 81 months, respectively." (PMID 32498288, 2020).
bacterial infections (3 papers, 2020 to 2024). "This suggests that as the bacterial infection intensifies, the RUNX1 splicing process in host cells is disrupted, altering its expression pattern and potentially increasing the risk of cell transformation." (PMID 39272372, 2024). "In the time-series analysis, the expression of RUNX1 gradually increased with the severity of bacterial infection, probably due to bacterial interference and the disruption of the cellular regulatory system." (PMID 39272372, 2024). "The identified RUNX1 target genes belong to the T and B cell signaling pathways, making them novel potential targets for the diagnosis and therapy of bacterial infections and other immune disorders." (PMID 32171242, 2020).
infectious disease (3 papers, 2010 to 2020). A disorder directly resulting from the presence and activity of a microbial, viral, or parasitic agent in humans. "Further study is required to examine the diverse array of functions of CD82 and RUNX1, the complexity of the regulation of CD82–RUNX1–Rab5/22, and the prospects for targeting CD82 as a therapeutic approach for the treatment of various infectious diseases." (PMID 29760437, 2018).
retinopathy (3 papers, 2020 to 2024). "Given that small-molecule inhibitors against RUNX1 have proven effective in experimental models of PH and retinopathy (see section "Eye/endothelium"), future work should address their efficacy in the context of DS-associated PH." (PMID 37670378, 2023). "Some reports show that the inhibition of RUNX1 activity results in the reduction of neovascular tufts in retinopathy, suggesting that RUNX1 has a close relationship with angiogenesis." (PMID 32319515, 2020). "Some reports show that inhibition of RUNX1 activity with the small molecule resulted in a significant reduction in neovascular tufts in oxygen-induced retinopathy, supporting the feasibility of targeting RUNX1 in aberrant retinal angiogenesis." (PMID 32319515, 2020). "Finally, the RUNX1 small-molecule inhibitor Ro5-3335 induced a significant reduction of neovascular tufts in oxygen-induced retinopathy models." (PMID 37670378, 2023).
breast (2 papers, 2024). "We therefore provide evidence that elevated expression of PTGS2 induced by RUNX1 contributes to colorectal tumorigenesis." (PMID 38778047, 2024).
digestive system tumors (2 papers, 2019 to 2024). "The results revealed that RUNX1 expression is substantially higher in the majority of digestive system tumors, suggesting a potential pro-oncogenic function of RUNX1 in the human digestive system." (PMID 39309442, 2024).
skeletal disease (2 papers, 2021 to 2023). "In mammals, three RUNX members, namely RUNX1, RUNX2, and RUNX3, play distinct and redundant roles, although RUNX2 is a dominant factor in skeletal development and several skeletal diseases." (PMID 37436583, 2023).